HRAS (HRas proto-oncogene, GTPase)
Diseases named in the same sentence as HRAS in open-access papers (continued):
Sharing a sentence is not in itself a finding about the gene and the disease.
osteosarcoma (9 papers, 2012 to 2024). A usually aggressive malignant bone-forming mesenchymal neoplasm, predominantly affecting adolescents and young adults. "Among them, the key hub genes were ICAM1 (intercellular adhesion molecule 1), HRAS (Ras family small GTP binding protein H‐Ras), PTGS2 (prostaglandin‐endoperoxide synthase 2, also known as COX‐2), and FOS (FBJ osteosarcoma oncogene)." (PMID 36772869, 2023). "Finally, the most interesting novel somatic mutations that occurred on trunks and branches were activating mutations of the RAS GTPases KRAS and HRAS that predispose to non‐ossifying fibromas and malignant giant cell tumors of the bone but have not been reported in osteosarcoma thus far." (PMID 33963544, 2021).
papillary thyroid cancer (9 papers, 2004 to 2024). "BRAFV600E, KRAS variants, NRAS variants, and HRAS variants have also been observed in papillary carcinoma originating from struma ovarii." (PMID 36975488, 2023). "In our opinion, the strong correlations of the (not yet assigned to a pathway) NEMP1 gene with the oncogenes TFG and HRAS indicate its potential role in the papillary thyroid cancer." (PMID 31349573, 2019). "We analyzed mutation status of BRAF and RAS (HRAS, NRAS, and KRAS) oncogenes in 34 papillary thyroid cancer samples using MALDI-TOF-MS." (PMID 24367375, 2013). "The mutual exclusivity of the NRAS, HRAS, and BRAF mutations in THCA tumors has been interpreted to mean that these mutations must have interchangeable effects on MAPK signaling activation, the main cancer-driving event in papillary thyroid carcinomas." (PMID 29125844, 2017). "We compared the ERK score, a measure of ERK activity derived from RNAseq data, from RET-rearranged, BRAF mutant, and RAS mutant papillary thyroid cancers in TCGA patients, and we found that RET-rearranged cancers have significantly higher ERK scores than either BRAF or NRAS/HRAS mutant tumors." (PMID 35510953, 2022).
rhabdomyosarcoma (9 papers, 2014 to 2025). A rare aggressive malignant mesenchymal neoplasm arising from skeletal muscle. "Here, we report on a pediatric patient showing a diffuse EN at birth associated with a postzygotic activating missense variant in HRAS (p.Gly13Arg), who developed a left paratesticular embryonic rhabdomyosarcoma." (PMID 37636262, 2023). "To date, five patients carrying somatic mutation in codon 35 of KRAS and codon 13 of HRAS with extensive EN and rhabdomyosarcoma have been reported." (PMID 37636262, 2023). "We describe the second case of a somatic variant in HRAS (c.37G>C, p.Gly13Arg) causing EN and contributing to rhabdomyosarcoma, the latter process involving multiple gains of the entire paternal chromosome 11 carrying the mutated HRAS allele." (PMID 37636262, 2023). "Although HRAS mutations have been reported in malignant fibrous histiocytoma (MFH), leiomyosarcoma, and rhabdomyosarcoma, HRAS mutation is a relatively uncommon event in liposarcoma." (PMID 24695632, 2014). "RAS mutations (including those in HRAS, NRAS and KRAS) occur in approximately 25% of cases of fusion-negative (embryonal) rhabdomyosarcoma (RMS) and may occur at a higher frequency in younger patients." (PMID 35459782, 2022).
angiosarcoma (8 papers, 2010 to 2024). A malignant tumor arising from the endothelial cells of the blood vessels. "Moreover, in the Angiosarcoma Project NRAS was mutated in two breast ASs and one cutaneous AS, while HRAS was mutated in two ASs of the breast." (PMID 38137511, 2023). "In angiosarcomas, activating RAS mutations (HRAS and NRAS) were identified in three samples (16%)." (PMID 34040639, 2021). "RAS had more frequent MYC, FLT4, CRKL, HRAS, and KMT2D alterations than sporadic angiosarcomas." (PMID 38256700, 2024).
diabetes (8 papers, 2007 to 2023). "4EBP1 was also positively associated with genes coupled to diabetes pathways, genes regulated by the transcription factors E2F, USF and SP1, the oncogenes HRAS and HOXB13 and several genes involved in negative regulation of translational initiation (EIF4EBP2, EIF2B3, EIF2C2)." (PMID 26698305, 2015). "Furthermore, the following genes are involved in diabetes and insulin signaling: MDH2, PPP1CA and HRAS." (PMID 26938218, 2016).
endometrial cancer (8 papers, 2015 to 2023). Primary or metastatic malignant neoplasm involving the endometrium (mucous membrane that lines the endometrial cavity). "Deletion of WT HRAS lead to decreased proliferation and increased apoptosis in KRAS-mutated endometrial cancer cells." (PMID 33924994, 2021). "In KRAS-mutated endometrial cancer cells, individual deletion of WT HRAS or NRAS limited proliferation in cancer cells, but not xenograft tumor growth." (PMID 33924994, 2021). "In KRAS-mutated endometrial cancer the wild-type KRAS allele antagonizes tumorigenesis, whereas wild-type HRAS supports transformation in vitro but not in vivo." (PMID 36607281, 2023).
breast tumor (7 papers, 2007 to 2024). "As determined by semi-quantitative RT-PCR, expression of StAR mRNA was evidently high in breast tumors induced by Neu, HRAS, and PyMT oncogenes, when compared with either TNBC or normal mouse mammary tissue." (PMID 36614200, 2023).
COVID-19 (7 papers, 2021 to 2024). A disease caused by infection with severe acute respiratory syndrome coronavirus 2. "Exposure to CS or nicotine upregulated many genes within AGE-RAGE signalling with high confidence, including CCND1, CXCL8, HRAS, IL6, KRAS and TNF, suggesting that smokers have a hyperactive AGE-RAGE and are therefore more at risk of severe COVID-19." (PMID 38991709, 2024). "Furthermore, we observed that the major transcript of multiple genes switched to a different transcript (isoform switching) between COVID-19 patients and controls, such as IL2, IL34, SERPINE2, NCBP1, HRAS, PRPF6, NCBP2, and LUC7L2." (PMID 35421082, 2022).
salivary duct carcinoma (7 papers, 2015 to 2025). An aggressive, high grade adenocarcinoma that arises from the salivary glands. "PI3K mutations are also frequently found in salivary duct carcinomas, and the co-mutation of HRAS/PI3K has been reported." (PMID 40243851, 2025). "HRAS mutations are also detected in mucoepidermoid carcinomas, adenoid cystic carcinomas, acinic cell carcinomas, salivary duct carcinomas, and the incidence of HRAS mutations is reported to be 11.1–21%, which is relatively high compared to HNSCCs." (PMID 40243851, 2025). "This is, to the best of our knowledge, the largest clinical case series of AR+, PIK3CA/HRAS co-mutated salivary duct carcinoma." (PMID 37427101, 2023). "A subgroup of salivary duct carcinoma (SDC) harbor overexpression of the androgen receptor (AR), and co-occurring mutations in the HRAS- and PIK3CA-genes." (PMID 37427101, 2023).
Spitz nevi (7 papers, 2011 to 2024). "Among the true pathogenic mutations, we found a mutation in HRAS (Q61K) in a desmoplastic Spitz nevus and in an atypical Spitz tumor, confirming the Spitz lineage of these lesions." (PMID 38791877, 2024). "“HRAS,” a proto-oncogene located on chromosome 11p, is the first genetic aberration that was associated with Spitz nevi." (PMID 35747831, 2022). "While HRAS appears to be rarely mutated in common acquired or congenital nevi, mutations in this gene occur in about 10–15% of Spitz nevi, particularly in desmoplastic variants." (PMID 34205480, 2021). "HRAS mutation analysis seems to be useful in the differential diagnosis between Spitz nevus and Spitzoid melanoma, and the presence of HRAS mutations is a marker of benignity and/or favorable clinical outcome." (PMID 32850962, 2020). "In the series reviewed, HRAS mutations and gene amplification were noted to be present in 0–24% of Spitz nevi." (PMID 21754924, 2011). "Moreover, HRAS has been shown to be mutated in Spitz nevi both by CNVs (12/102; 12%) and point mutations (8/12; 67%)." (PMID 32850962, 2020). "However, it is likely that the reported incidence of HRAS mutations has been artificially deflated by the inclusion of certain nevi with histological classifications that are similar but likely unrelated to Spitz nevi in the literature." (PMID 21754924, 2011). "The reason why mutations in HRAS lead to Spitz nevi is unclear but could be related to higher affinity for the PI3K-PKB/AKT pathway which would be able to drive the symmetrical overgrowth of cells with an epithelioid morphology without marked activation of the melanizing pathways." (PMID 32850962, 2020). "It would follow that preferential PI3K-PKB/AKT activation through HRAS drives the symmetrical overgrowth of cells with an epitheliod morphology without marked activation of the melanizing pathways (since the majority Spitz nevi are largely amelanotic)." (PMID 21754924, 2011).
adenoma (6 papers, 2004 to 2025). A neoplasm arising from the epithelium. "The two mutation-positive ≥4-cm adenomas had fusion PAX8/PPARG and mutant HRAS." (PMID 31780751, 2019).
ameloblastoma (6 papers, 2018 to 2023). The most common odontogenic tumor, arising from the epithelial component of the embryonic tooth and usually affecting the molar-ramus region of the mandible or maxilla. "In a similar way, other somatic mutations have been reported in ameloblastoma, mainly affecting: SMO, other MAPK pathway-related genes such as KRAS, NRAS, HRAS, FGFR2 and in a lower frequency, PTEN and CTNNB1 among others." (PMID 35048068, 2021). "Remarkably, the unilocular to multilocular pattern rate was higher (1.3:1, 1.5:1, respectively) in the tumors with BRAF and multiple gene mutations, in contrast to SMO, NRAS, HRAS, and EGFR-mutated ameloblastomas (1:3, 1:2, respectively)." (PMID 29388014, 2018). "However, other Authors showed additional mutations to B-Raf in ameloblastomas, such as NRAS, HRAS, KRAS, FGFR2, and PIK3CA,10,23,44 suggesting they may represent secondary mutations occurring later in the pathogenesis of ameloblastoma." (PMID 35468886, 2022). "Mutually exclusive and less common mutations affecting other MAPK-related genes, such as KRAS, NRAS, HRAS, and FGFR2 (a receptor whose stimulation activates MAPK/ERK pathway) have been reported in BRAF wild-type ameloblastomas." (PMID 35048058, 2021).
differentiated thyroid carcinoma (6 papers, 2017 to 2026). Differentiated thyroid carcinoma (DTC), also known as papillary or follicular thyroid carcinoma, is a slow-growing malignancy usually presenting in adults as an asymptomatic thyroid mass. "This study was designed with the aim of examining the relationship between clinicopathological characteristics and mutations in the BRAF, HRAS, KRAS, and NRAS genes with metastatic disease and RAIR development in patients with differentiated thyroid cancer." (PMID 40104288, 2025). "The aim of this study was to investigate the relationship between the presence of the BRAF, HRAS, NRAS, and KRAS gene mutations and the development of dedifferentiation (iodine-refractory disease) and extrathyroidal disease in patients with differentiated thyroid carcinoma (DTC)." (PMID 40104288, 2025).
nasopharyngeal carcinoma (6 papers, 2017 to 2022). A carcinoma arising from the nasopharyngeal epithelium. "In nasopharyngeal carcinoma, circZNF609 sponges miR-338-3p to promote cell glycolysis, invasion, migration, and proliferation by regulating HRAS." (PMID 35236250, 2022). "Mechanistically, H19 upregulates the expression of its downstream proto-oncogene HRAS (HRas proto-oncogene, GTPase) by sponging miRNA let-7, thus promoting the carcinogenic activity of HRAS in nasopharyngeal carcinoma." (PMID 33520725, 2020). "Additionally, the mRNA level of HRAS was significantly lower in nasopharyngeal carcinoma cells compared to CAL33 and AMC-HN-8." (PMID 36012290, 2022).
oral squamous cell carcinoma (6 papers, 2014 to 2025). "In addition, HRAS H27H polymorphism was statistically associated with the risk of developing various cancers (gastric, thyroid, bladder, and oral squamous cell carcinoma) and was detected both in tumor and in blood samples." (PMID 25360634, 2014). "The knockdown of DPP9 in oral squamous cell carcinoma cells increased cell growth via FAP-α, whereas the overexpression of DPP9 in Huh-7 and HepG2 cells reduced proliferation and increased apoptosis independent of its enzymatic activity by interacting with HRAS." (PMID 37626841, 2023).
renal carcinoma (6 papers, 2008 to 2022). A carcinoma arising from the epithelium of the renal parenchyma or the renal pelvis. "For example, tipifarnib is a farnesyltransferase inhibitor targeting HRAS that increases anti-cancer effects through the prevention of apoptosis of T cells and downregulation of the level of cellular PD-L1 of renal cancer cells." (PMID 36077620, 2022). "Finally, HRAS v13 and v15 were notably expressed only in liver and renal carcinomas." (PMID 34948093, 2021).
autism (5 papers, 2012 to 2025). Persistent deficits in social interaction and communication and interaction as well as a markedly restricted repertoire of activity and interest as well as repetitive patterns of behavior. "Our identification of rare damaging variants in the HRAS and MAP2K2 genes further suggests that dysregulation of the Ras/ERK pathway may contribute to autism risk." (PMID 22558107, 2012).
colorectal tumors (5 papers, 2002 to 2024). "Therefore this study provides for the first time, a comparative study of BRAF, KRAS and HRAS oncogenes regarding their differential regulation of autophagic markers and related properties in colorectal tumor cells." (PMID 26802026, 2016).
thyroid (5 papers, 2015 to 2025). "The objective of the study was to determine if the analysis of mutations (BRAF, NRAS, KRAS and HRAS) using readily available molecular techniques can help better classify indeterminate thyroid nodules." (PMID 26621130, 2015). "Taking NRAS and HRAS for instance, they are members of oncogenic RAS and the clinical impact of RAS mutations on the management of thyroid nodules with indeterminate cytology is unsatisfactory." (PMID 36137089, 2022). "Our analysis, however, highlights substantial differences in DNAm between BRAF-mutated vs. NRAS- and HRAS-mutated THCA tumors; moreover, the differences in DNAm appear to profoundly shape gene expression profiles, which may contribute to thyroid tumorigenesis." (PMID 29125844, 2017).
urothelial carcinoma (5 papers, 2020 to 2025). A malignant neoplasm derived from the transitional epithelium of the urinary tract (urinary bladder, ureter, urethra, or renal pelvis). "The pathogenetic pathway of superficial noninvasive urothelial carcinoma is characterized by FGFR3, tyrosine receptor, HRAS and PI3KCA mutations." (PMID 39118085, 2024). "HRAS overexpression is being detected in recurrent non-invasive urothelial carcinoma." (PMID 39118085, 2024).
cholangiocarcinoma (4 papers, 2017 to 2024). A carcinoma that arises from the intrahepatic biliary tree (intrahepatic cholangiocarcinoma) or from the junction, or adjacent to the junction, of the right and left hepatic ducts (hilar cholangiocarcinoma). "Regarding cholangiocarcinoma, HRAS, KIT and FAS have previously been associated with cholangiocarcinoma in the literature." (PMID 28178311, 2017). "Examining cholangiocarcinoma, we observed that the HRAS, KIT, ZBTB16, FAS and NCOA4 genes were altered by high methylation (shown in light sea green)." (PMID 28178311, 2017).
embryonal rhabdomyosarcoma (4 papers, 2011 to 2025). A poorly circumscribed morphologic variant of rhabdomyosarcoma. "The two main subtypes are alveolar rhabdomyosarcoma (ARMS), which is associated with PAX3/7-FOXO1 fusion genes, and embryonal rhabdomyosarcoma (ERMS), which is associated with mutations in common cancer genes such as HRAS, KRAS, NRAS, CTNNB1, PIK3CA and TP531." (PMID 30353028, 2018).
kidney cancer (4 papers, 2016 to 2022). Primary or metastatic malignant neoplasm involving the kidney. "HRAS is a member of the ras oncogene family, whose mutations are involved in the occurrence of bladder, thyroid, salivary ductal, epithelial-myoepithelial, and kidney cancer 18-19." (PMID 33162802, 2020).
linear sebaceous nevus syndrome (4 papers, 2021 to 2025). "Further research in this direction will allow understanding the association of HRAS mutations with the development of skeletal anomalies in SFMS syndrome." (PMID 41438146, 2025). "Almost simultaneously, it was demonstrated that nevus sebaceous and linear sebaceous nevus syndrome are also caused by postzygotic HRAS and KRAS mutations." (PMID 34208656, 2021). "Schimmelpenning-Feuerstein-Mims syndrome (SFMS, Solomon syndrome, Schimmelpenning syndrome) is an orphan disease associated with pathogenic variants in the HRAS, KRAS, or NRAS genes in mosaic form." (PMID 41438146, 2025).
lung squamous cell carcinoma (4 papers, 2013 to 2023). "Overexpression of HRAS gene was observed in the blood group of smokers and tended to be more presumable in squamous cell lung cancer, while HRAS mRNA expression in tissue was increased in adenocarcinoma." (PMID 33549031, 2021). "Study of the TCGA data corroborates that both HRAS and TP63 expression are significantly elevated in advanced stage HNSCCs and early-stage lung squamous cell carcinoma (LSCC) compared to normal tissue." (PMID 37638000, 2023).
Obesity (4 papers, 2015 to 2025). Accumulation of substantial excess body fat. "For instance, HRAS G12S heterozygous mutant mice displayed resistance to HFD-induced obesity but exhibited impaired hepatic energy homeostasis compared to wild-type mice." (PMID 40438591, 2025). "In the present investigation, we observed that Cpn notably decreased the upregulation of HRAS expression in adipose tissue induced by a WD, suggesting that HRAS may be a potential target for Cpn in alleviating obesity." (PMID 40438591, 2025).
pancreatic ductal adenocarcinoma (4 papers, 2021 to 2025). An infiltrating adenocarcinoma that arises from the epithelial cells of the pancreas. "The RAS family of oncoproteins (KRAS, HRAS, and NRAS) drive aggressive cancers like pancreatic ductal adenocarcinoma (PDAC) and non-small cell lung cancer (NSCLC), yet targeting mutant RAS has historically been challenging due to its “undruggable” structure." (PMID 41471277, 2025). "In pancreatic ductal adenocarcinoma, KRAS mutations dominate (~90–95%), especially at codon 12 (G12D, G12V, G12R), while NRAS and HRAS mutations are essentially absent." (PMID 41515890, 2025).
renal cell carcinoma (4 papers, 2022 to 2023). "QPCT (glutaminyl-peptide cyclotransferase) is bound to HRAS and improves the stability of HRAS by inhibiting its ubiquitination degradation, which can activate the ERK signaling pathway and lead to sunitinib resistance in renal cell cancer." (PMID 36789694, 2022). "Based on the KEGG analysis, G6PD was enriched in central carbon metabolism in cancer, and HRAS and NRAS could be involved in many signaling pathways, such as AGE-RAGE signaling pathway in diabetic complications, human cytomegalovirus infection and renal cell carcinoma." (PMID 37143953, 2023).